ADAM7 (ADAM metallopeptidase domain 7)
Description:
Required for normal male fertility via maintenance of epithelial cell morphology in the caput epididymis and subsequently correct epididymis lumen structure required for sperm development (By similarity). Plays a role in sperm motility, flagella morphology and tyrosine phosphorylation during sperm capacitance (By similarity). Plays a role in normal expression levels of HSPA5, ITM2B and ADAM2 in sperm both prior to and post-capacitation (By similarity). This is a non catalytic metalloprotease-like protein (By similarity).
Synonyms: ADAM 7; GP83; GP-83; EAPI; ADAM-7
Tractability: Antibody: UniProt predicts a signal peptide or a membrane-spanning region; its Gene Ontology location is reachable by antibodies, with medium confidence. PROTAC: ubiquitination databases record sites on it.
Gene: Protein-coding gene on chromosome 8 (24,440,930 to 24,526,970, forward strand). Ensembl gene ENSG00000069206.
Subcellular location: Membrane
Gene Ontology:
Molecular function: metalloendopeptidase activity; endopeptidase activity; metallopeptidase activity
Biological process: epididymis development; epithelial cell morphogenesis; positive regulation of flagellated sperm motility; positive regulation of sperm capacitation; proteolysis
Cellular component: plasma membrane; cell surface; membrane
Genetic constraint (gnomAD): Loss-of-function variants: 68 observed, 71.73 expected, observed/expected ratio (o/e) 0.95, 90% interval 0.78 to 1.16. The upper end of that interval is the gene's LOEUF score, 1.16, which puts it in group 5 of 6, group 1 being the genes least tolerant of losing a copy. Missense variants: 804 observed, 772.27 expected, observed/expected ratio (o/e) 1.04, 90% interval 0.98 to 1.1. Synonymous variants: 266 observed, 264.03 expected, observed/expected ratio (o/e) 1.01, 90% interval 0.91 to 1.12.
Homologues: Orthologues: chimpanzee ADAM7 (98% identical), macaque ADAM7 (94% identical), rabbit ADAM7 (73% identical), dog ADAM7 (72% identical), guinea pig ADAM7 (71% identical), mouse Adam7 (68% identical), rat Adam7 (68% identical), pig ADAM7 (67% identical), tropical clawed frog XB990656 (27% identical), zebrafish adam9b (26% identical), Caenorhabditis elegans unc-71 (25% identical), Drosophila melanogaster mmd (19% identical), and 4 more. Paralogues in human: ADAM28 (36% identical), ADAM8 (30% identical), ADAM12 (30% identical), ADAM19 (28% identical), ADAM33 (27% identical), ADAM9 (26% identical), ADAM15 (25% identical), ADAM22 (25% identical), ADAM30 (25% identical), ADAM23 (25% identical), ADAM20 (24% identical), ADAM29 (24% identical), and 8 more.
Diseases named in the same sentence as ADAM7 in open-access papers:
ADAM7 is named in the same sentence as 13 diseases in open-access papers, as found by Europe PMC text mining. Sharing a sentence is not in itself a finding about the gene and the disease. The quoted sentences say what the papers report.
prostate carcinoma (2 papers, 2013 to 2021). A carcinoma that arises from epithelial cells of the prostate gland. "The alternative expression levels of these genes in certain organs may act as an indicator of cancer development, including WFDC2 in ovarian cancer, ADAM29 and ADAM7 in melanoma and Eppin in prostate cancer." (PMID 24137416, 2013).
COVID-19 (1 paper, 2022). A disease caused by infection with severe acute respiratory syndrome coronavirus 2. "We found that the expression of the antiviral genes negatively correlated (except ADAM7, ADAM11, ADAM12, ADAM18, ADAM20, and ADAM29) with the HRCT score of the COVID-19 patients suggesting association of increased antiviral response with decreased disease severity." (PMID 36532041, 2022).
hepatocellular carcinoma (1 paper, 2020). A malignant tumor that arises from hepatocytes. "By targeting ADAM metallopeptidase domain 7 (ADAM7) and pyruvate kinase M1/2 (PKM), miR-122 negatively affects in vitro invasion, migration, and survival of hepatocellular carcinoma cells." (PMID 33066509, 2020).
metastatic melanoma (1 paper, 2024). A melanoma that has spread from its primary site to another anatomic site. "While the normal function of ADAM7 is in the epididymis, a study of somatic ADAM mutations present in human cutaneous metastatic melanoma found that ADAM7 was frequently mutated and many of these mutations led to decreased cell adhesion to collagen IV and laminin and increased cell migration." (PMID 39050735, 2024).
cancer (3 papers, 2012 to 2024). A tumor composed of atypical neoplastic, often pleomorphic cells that invade other tissues. "Pan-cancer SNV analysis revealed relatively high mutation frequencies in ADAM29, ADAM7, and ADAM18, with mutations predominantly observed in SKCM and UCEC." (PMID 39346916, 2024).
tumor (2 papers, 2014 to 2024). "Conversely, ADAM7 and ADAM21 displayed lower levels of methylation in tumor tissues compared to normal tissues." (PMID 39346916, 2024). "Using a combined geneset of these 5 remaining cell cycle-related genes (BUB1B, CCNB1, CCNB2, TTK and CDK1) as well as ADAM7 and FAM72B, we also observed a statistically-significant reduction in disease-free survival of patients with tumours exhibiting alterations in gene expression (p = 0.015)." (PMID 25519703, 2014). "Survival analysis identified a statistically-significant reduction in disease-free survival of patients with tumours exhibiting alterations in expression of this geneset (p = 0.023) which was lost when FAM72B and ADAM7 were removed from the geneset (p > 0.05) (data not shown)." (PMID 25519703, 2014).
ADAM7 also shares sentences with these, for which no sentence is quoted: infection (4 papers); Chagas disease (2); parasitemia (2); melanoma (1); ovarian carcinoma (1); prostate tumours (1); psychiatric disorder (1).